MIR370 (microRNA 370)
Synonyms: hsa-mir-370; MIRN370; mir-370
Gene: MicroRNA gene on chromosome 14 (100,911,139 to 100,911,213, forward strand). Ensembl gene ENSG00000199005.
Gene Ontology:
Biological process: cellular response to leukemia inhibitory factor; miRNA-mediated post-transcriptional gene silencing; negative regulation of gene expression
Cellular component: RISC complex
Homologues: Orthologues: chimpanzee ptr-mir-370 (100% identical), pig ssc-mir-370 (100% identical), dog MIR370 (97% identical), guinea pig MIR370 (96% identical), rat Mir370 (95% identical), mouse Mir370 (93% identical).